CRP (C-reactive protein)
Diseases named in the same sentence as CRP in open-access papers (continued):
Sharing a sentence is not in itself a finding about the gene and the disease.
appendicitis (continued). "Median CRP level was significantly higher in the appendicitis group (44.3 mg/L; IQR 21.5–113.1) compared to controls (1.1 mg/L; IQR 0.4–3.9) (p < 0.001)." (PMID 40871545, 2025). "Our study supports the use of CRP as a predictive factor for acute appendicitis on post-operative histopathology, and by extension as a marker to delineate patients who do not require appendicectomy." (PMID 41523465, 2025). "Other studies present similar age-related shifts in inflammatory parameters, with elevated NLR, PLR, and CRP in elderly patients presenting with complicated appendicitis." (PMID 40735314, 2025). "Further testing and laboratory workup can help raise suspicion, but they remain non-specific, as leucocytosis and elevated C-reactive protein (CRP) can be observed in both adnexal torsion and appendicitis." (PMID 41179099, 2025). "Recent studies have highlighted the potential role of inflammatory markers such as the Neutrophil‐to‐Lymphocyte Ratio (NLR), Monocyte‐to‐Lymphocyte Ratio (MLR), and C‐reactive protein (CRP) in diagnosing appendicitis in adults." (PMID 40317523, 2025). "The aim of this study was to assess the diagnostic accuracy of immature granulocyte count and neutrophil-to-lymphocyte ratio in acute appendicitis against traditional markers like white blood cell count and C-reactive protein." (PMID 40531775, 2025). "CRP is an easily obtainable and cost-effective biochemical marker, and as such should be a routine investigation in children with clinical concerns for acute appendicitis." (PMID 41523465, 2025). "Serum CRP demonstrated strong discriminatory power in identifying children with pathohistologically confirmed acute appendicitis." (PMID 40871545, 2025). "Variables significantly associated with appendicitis were identified and used to create a new scoring system (CHANSE: CRP elevation, Heel drop test positivity, Anorexia, Nausea or vomiting, Shift to the left, Elevated WBC)." (PMID 41473919, 2025). "CRP is a valuable adjunctive inflammatory marker in acute appendicitis, with recent studies reporting a sensitivity of approximately 87% and a specificity of around 77% at a 10 mg/L cut-off in adult patients." (PMID 40871545, 2025). "This study highlights the diagnostic value of combining inflammatory markers—NLR, MLR, NMR, PLR, NPR, and CRP—in the preoperative evaluation of appendicitis in pediatric patients." (PMID 40317523, 2025). "CRP was found to be a superior predictor of acute appendicitis following receiver operating characteristic (ROC) analysis (area under the curve (AUC) 0.712, sensitivity 75.60%, specificity 61.48%, p<0.001) compared to NLR, neutrophil and lymphocyte count." (PMID 41523465, 2025). "The appendicitis group presented with an average temperature of 36.8 °C, CRP of 5.85 mg/dL, and leucocyte count of 12.82/μL; controls showed an average temperature of 36.6 °C, CRP of 1.19 mg/dL, and leucocyte count of 8.14/μL." (PMID 41010329, 2025). "An increase in complicated appendicitis was observed during the war in medical centers close to conflict zones, along with a trend toward increased CRP levels in this population." (PMID 40648989, 2025). "The results of our study do not support an introduction of LRG1 in clinical practice to help differentiate between uncomplicated and complicated appendicitis, since both CRP and AIR scored showed better discriminative performances." (PMID 40208339, 2025). "Using mass spectrometry (SIM MS), they found LRG levels were >100-fold higher in appendicitis patients vs. controls (AUC = 0.98, 95% CI 0.96–1.0), outperforming standard markers like CRP (AUC = 0.76) and neutrophil count (AUC = 0.73)." (PMID 40547910, 2025). "Patients with CRP <100 mg/l at 24 h of antibiotic treatment for uncomplicated acute appendicitis have a 99% likelihood of successful antibiotic therapy." (PMID 40741675, 2025).
appendicitis (continued). "In the present study, high CRP levels were seen in patients diagnosed with acute appendicitis gradually increasing with the symptom onset time." (PMID 40572758, 2025). "While CRP is highly sensitive in detecting serious conditions such as acute perforated appendicitis, complicated diverticulitis, and severe pancreatitis." (PMID 40067493, 2025). "Univariate analysis indicated that age, body temperature, symptom duration, CRP, and other factors pose risks for perforated appendicitis." (PMID 38509094, 2024). "This study differed from ours in several vital aspects, including a smaller sample size, a restricted study population limited to uncomplicated appendicitis cases, and the analysis of CRP solely as a categorical variable." (PMID 39726534, 2024). "This study aims to fill this gap by conducting an evaluation of the CRP to prealbumin ratio (CPA) as a potential marker for pediatric perforated appendicitis." (PMID 38509094, 2024). "Particularly, elevated levels of CRP and procalcitonin in the perforated appendicitis group suggested a more severe inflammatory and infectious state." (PMID 38509094, 2024). "Recent research indicates that serum CRP levels upon admission can serve as a prognostic indicator for acute appendicitis in pediatric patients." (PMID 39726534, 2024). "MAS used in combination with CRP is a highly sensitive tool for use in the diagnosis of acute appendicitis and is especially useful in resource-limited healthcare settings and for assistance in decision-making for doctors with less clinical experience." (PMID 39677268, 2024). "Several objective variables are known to be predictive for differentiation between complicated and uncomplicated appendicitis, e.g., age and CRP levels." (PMID 38228896, 2024). "NLR, platelet-to-lymphocyte ratio (PLR), and C-reactive protein (CRP) were significantly higher in patients with complicated appendicitis (p < 0.05)." (PMID 39624500, 2024). "Laboratory test results for appendicitis showed significantly elevated levels of C-reactive protein, leukocytes, neutrophils, as well as a notably lower potassium concentration." (PMID 39716296, 2024). "NEU (p = 0.014), CRP levels (p = 0.002), time from symptom onset to operation (p = 0.004), and appendicitis diameter (p = 0.017) were positively significant between operation time." (PMID 39336992, 2024). "A previous study in the child population demonstrated that children with a CRP level on admission ≥10 mg/L were over seven times more likely to have appendicitis than those with CRP level <10 mg/L." (PMID 38929896, 2024). "When it comes to predicting perforation in acute appendicitis, C-reactive protein (CRP) is more effective than bilirubin." (PMID 38989359, 2024). "Our study showed that in patients with high MAS and raised CRP levels, the probability of acute appendicitis was high." (PMID 39677268, 2024). "In clinical practice, CRP and leucocyte count are commonly used laboratory markers for the diagnosis of suspected acute appendicitis." (PMID 39451658, 2024). "Currently, CRP is extensively utilized in diagnosing appendicitis in children and distinguishing complicated appendicitis." (PMID 39726534, 2024). "Acute inflammatory markers in the laboratory showed significantly higher values in the group of patients with acute appendicitis: C-reactive protein (p = 0.009), White blood cells (p = 0.001) and neutrophils (p < 0.001)." (PMID 38892909, 2024). "The existing literature underscores a notable increase in WBC and CRP levels among patients diagnosed with acute appendicitis during the COVID-19 pandemic compared to pre-pandemic periods." (PMID 38770054, 2024). "Further studies with larger patient cohorts are required to better characterise CRP levels in acute appendicitis and its potential clinical role." (PMID 39120614, 2024).
appendicitis (continued). "The predictive value positive (PV+) of a screening test is the probability that a person has the disease (acute appendicitis) given that the test is positive (positive CRP/MAS)." (PMID 39677268, 2024). "Biochemical markers such as total leucocyte count (TLC) and C- reactive protein (CRP) have been widely used in diagnosing acute appendicitis and differentiating complicated and uncomplicated appendicitis." (PMID 37143626, 2023). "Multivariate regression analysis showed that third trimesters (P = 0.013, OR = 16.81), CRP level ≥ 34.82 mg/L (P = 0.007, OR = 6.24) and NEUT% ≥85.35% (P = 0.011, OR = 18.05) were independent risk factors for complicated appendicitis." (PMID 37393302, 2023). "Our research has confirmed significantly higher CRP values in children with clinical symptoms of acute appendicitis at the moment of hospital admission." (PMID 37509519, 2023). "There are several scoring systems, including the Alvarado score, which attempt to combine the ‘classical’ signs of appendicitis with certain blood results, including white cell count and C-reactive protein, to predict the likelihood of appendicitis." (PMID 37575745, 2023). "Particularly, a retrospective study with 498 patients who had appendectomy illustrated that CRP was great validity of detecting and distinguishing between complicated and uncomplicated appendicitis." (PMID 37090195, 2023). "Our study also demonstrated a higher specificity of elevated bilirubin levels for perforated appendicitis (80.97%) than CRP (26.72%)." (PMID 37929270, 2023). "When assessing a diagnosis of acute appendicitis in a pediatric population displaying acute abdominal pain, CRP complements the history and physical examination." (PMID 37048540, 2023). "Further multivariate regression analysis showed that third trimesters (P = 0.013, OR = 16.81), CRP level ≥ 34.82 mg/L (P = 0.007, OR = 6.24) and NEUT% ≥85.35% (P = 0.011, OR = 18.05) were independent risk factors for complicated appendicitis." (PMID 37393302, 2023). "Experiments have shown that peripheral blood WBC count and CRP are the best laboratory methods for diagnosing acute appendicitis." (PMID 37849798, 2023). "C-reactive protein (CRP) is frequently used in suspected appendicitis, but its specificity varies across studies." (PMID 37929270, 2023). "Backward stepwise regression analysis using AIC in a logistic regression analysis model eventually revealed a significant association between the following 3 variables and complicated appendicitis: third trimesters, CRP ≥ 34.82 mg/L, and NEUT% ≥85.35%." (PMID 37393302, 2023). "In fact, our simplified predictive model considers only low lymphocyte count and high CRP to albumin ratio to significantly correlate with the presence of gangrenous appendicitis." (PMID 36707812, 2023). "A total of 152 patients out of 263 who were tested for CRP and had elevated levels had confirmed histological diagnosis of appendicitis." (PMID 37873039, 2023). "The WBC count and C-reactive protein levels are higher in blood tests of patients with appendicitis who were operated during the pandemic period." (PMID 36644328, 2023). "The mean C-reactive protein (CRP) level was 111.4 ± 34.1 mg/dL among patients presenting with simple appendicitis versus 150.3 ± 66.5 mg/dL among those having complicated appendicitis." (PMID 37303416, 2023). "These two variables—lymphocyte count and CRP/albumin ratio—resulted particularly abnormal in patients with gangrenous appendicitis." (PMID 36707812, 2023). "Prevailing inflammatory markers such as WBC and CRP are insufficient for establishing the diagnosis of appendicitis with a high level of specificity or sensitivity." (PMID 37048540, 2023). "Among them, WBC and CRP are the commonly used laboratory indicators for the diagnosis of acute appendicitis." (PMID 37849798, 2023).
appendicitis (continued). "The diagnostic efficacy of salivary LRG1 was compared with that of common laboratory biomarkers for appendicitis: the total white blood cell count, CRP, and neutrophil count." (PMID 37047015, 2023). "However, whether such CRP-QTLs are causally related to appendicitis risk remains unclear." (PMID 35693796, 2022). "For this analysis, 65,457 genome-wide significant CRP-QTLs from the Pan-UKBB cohort were intersected with the summary statistics from the appendicitis GWAs performed in the same cohort." (PMID 35693796, 2022). "C-reactive protein (CRP) was found to be superior to bilirubin for anticipation of perforation in acute appendicitis." (PMID 35223231, 2022). "Given the pleiotropic nature of many molecular phenotypes, one of the important observations of this study is the identification of shared genetic loci between CRP concentrations and appendicitis." (PMID 35693796, 2022). "Variables in the model after multivariate analysis were age, CRP, complicated appendicitis on imaging, surgery more than 8 h after presentation, and presenting at nighttime." (PMID 35453836, 2022). "Some of the long-standing factors that have been utilised in an attempt to pre-operatively diagnose appendicitis include measuring the serum C-reactive protein (CRP) and assessing for leucocytosis." (PMID 34515986, 2022). "On the basis of our results, we confirmed CRP eryptosis induction and the strong relationship between CRP and eryptosis in conditions of acute inflammation, such as peritonitis and acute appendicitis." (PMID 36498493, 2022). "Although we included fewer patients than required by our sample size calculation, the prevalence of appendicitis was higher than expected, possibly because GPs used the CRP test when they had a higher suspicion of appendicitis." (PMID 35535699, 2022). "The presence of an elevated CRP, INR, and lactate level was significantly associated with HP grade severity of appendicitis (p = 0.001, p = 0.001, and p = 0.002, respectively)." (PMID 35983388, 2022). "In the binary logistic regression analysis performed to analyze factors associated with complicated appendicitis, age, the number of daily new cases, DNI, and CRP were identified as relevant factors in the univariate analysis." (PMID 35433818, 2022). "Initial CRP levels were related to the specialist’s diagnosis of appendicitis, and the test’s characteristics were calculated for multiple cut-offs." (PMID 35535699, 2022). "When performing blood tests, white blood cells (WBC), especially neutrophils, and C-reactive protein (CRP) are usually high, with a sensitivity (Sn) of 79%, 95%, and 46%, respectively, in uncomplicated acute appendicitis (NCAA)." (PMID 36291361, 2022). "CRP was able to demonstrate perforation with higher sensitivity and specificity than complicated appendicitis only." (PMID 35495380, 2022). "Second, serum levels of CRP are directly correlated with the time of evolution of several inflammatory pathologies, including appendicitis." (PMID 36495332, 2022). "Our results prioritize HLX and CTSB as potential causal genes for appendicitis and suggest a shared genetic mechanism between appendicitis and CRP concentrations." (PMID 35693796, 2022). "•CRP was helpful not only as an independent marker of severity in acute appendicitis but also predicting complications and perforation as well with higher sensitivity." (PMID 35495380, 2022). "The present study adds to the existing literature, demonstrating a clear benefit from adding CRP to signs and symptoms when predicting appendicitis in children in primary care." (PMID 35535699, 2022). "Regarding analytical parameters, the measurement of leukocytes, C-reactive protein and ratio between neutrophils and lymphocytes was significantly higher in patients with complicated acute appendicitis." (PMID 35106154, 2022).
appendicitis (continued). "Several studies have shown that children with CRP values in the range of 10–50 mg/L suggest uncomplicated appendicitis, while CRP > 50 mg/L strongly suggests CA." (PMID 35431963, 2022). "This study sought to determine the diagnostic accuracy of four blood tests (white cell count (WCC), neutrophil(count or percentage), C reactive protein (CRP) and/or procalcitonin) for childhood appendicitis." (PMID 36328382, 2022). "In a study of patients with appendicitis the mean CRP was significantly higher in PWH compared to HIV-uninfected patients, despite similar clinical features." (PMID 35725387, 2022). "The PPV of all three parameters was most discriminating when predicting severity of appendicitis in the pediatric population, i.e., patients with a CRP>111 mg/L, an NLR>14, and a PLR>280 were more likely to have complicated appendicitis." (PMID 36185898, 2022). "On receiver operating characteristic (ROC) analysis, CRP has the highest specificity for complicated appendicitis and the highest positive likelihood ratio for both complicated and perforated appendicitis." (PMID 35495380, 2022). "CRP was well observed in our study to be an independent marker of severity in acute appendicitis with not only predicting complications but perforation as well with higher sensitivity." (PMID 35495380, 2022). "C-reactive protein (CRP) is one of the most abundant systemic markers of inflammation and one of the most important biomarkers in the diagnosis of acute appendicitis." (PMID 35693796, 2022). "After a multivariate analysis, it was found that only C-reactive protein was a good predictor of complicated acute appendicitis." (PMID 35106154, 2022). "CRP adds value to history and physical examination when diagnosing appendicitis in children presenting acute abdominal pain in primary care." (PMID 35535699, 2022). "TB, in combination with others such as WCC, CRP, and clinical presentation, is more sensitive and specific in identifying patients who would develop complicated appendicitis." (PMID 36237793, 2022). "CRP value > 6.15 mg/L has a sensitivity of 100.0% and a specificity of 54% in predicting complicated appendicitis according to another study, with a positive predictive value of 100% and a negative predictive value of 61.54%, similar to our results." (PMID 35495380, 2022). "In that setting, CRP is tested routinely in cases of suspected appendicitis, with imaging recommended before deciding to perform appendectomy." (PMID 35535699, 2022). "In a previous cohort study, children with appendicitis were less likely to be tested for CRP than children with appendicitis." (PMID 35535699, 2022). "Inflammation biomarkers commonly assessed include total and differential leukocyte count, C- reactive protein (CRP), or procalcitonin, but all of these markers lack the sensitivity and specificity to be used alone in making the diagnosis of appendicitis." (PMID 36676645, 2022). "When differentiating appendicitis in children presenting with acute abdominal pain in primary care, a CRP cut-off at ≥ 10 mg/L had a sensitivity and specificity of 0.87 and 0.77, respectively." (PMID 35535699, 2022). "It is curiously different than CRP values in other cases of viral acute appendicitis cases, as they describe CRP values ranging from 5 to 50 mg/L." (PMID 36013568, 2022). "Appendicitis is least likely if the CRP value is < 10 mg/L and symptoms have been present for > 48 h." (PMID 35535699, 2022). "Patients with complicated appendicitis exhibited substantially higher WCC, neutrophil, and CRP levels compared to those with uncomplicated appendicitis (14.15 vs. 12.88, p =0.016, 11.63 vs. 10.19, p = 0.007, and 89.28 vs. 40.65, p = 0.0001, respectively)." (PMID 36237793, 2022). "White cell counts (WCCs), absolute neutrophil counts (ANC), and c-reactive protein (CRP) are raised in patients diagnosed with acute appendicitis." (PMID 36185898, 2022).